LUM (lumican)
Diseases named in the same sentence as LUM in open-access papers (continued):
Sharing a sentence is not in itself a finding about the gene and the disease.
melanoma (continued). "Moreover, the lumcorin peptide corresponding to a sequence of 17 amino acids carried by the core protein of lumican inhibits melanoma cell chemotaxis in a manner similar to lumican protein." (PMID 34572532, 2021). "Initially, the lumican protein core was shown to inhibit melanoma cells’ migration." (PMID 34572532, 2021). "Likewise, the intensity of VEGF immunostaining and the abundance of blood vessels in melanoma lung metastasis nodules were decreased in lumican-expressing tumors." (PMID 34572532, 2021). "Moreover, the potential anti-metastatic role of lumican in melanoma by inhibiting the membrane-type matrix metalloproteinase (MMP)-14 activity and melanoma cell migration in vitro has been studied in vitro and in vivo." (PMID 34572532, 2021). "Lumican and its derived peptides were previously shown to decrease melanoma progression." (PMID 34638415, 2021). "One of the key examples is the role of lumican on melanoma cell adhesion and motility." (PMID 34572532, 2021). "On the other hand, in Snail-B16F1 melanoma cells treated with lumican, vinculin expression is significantly reduced, leading to the formation of fewer focal adhesions and inhibition of lamellipodia protrusions, further suggesting the anti-metastatic effect of lumican." (PMID 33917849, 2021). "Moreover, in a mouse model of B16F1 melanoma primary tumor growth, lumican treatment with the L9Mc peptide increased cancer cell apoptosis." (PMID 34572532, 2021). "The demonstrated inhibitory effect of lumican on melanoma cell invasion may suggest that lumican potentially inhibited cell migration by involvement of FAK phosphorylation in EMT-like melanoma cells." (PMID 33917849, 2021). "More recently, several studies confirmed that lumican was synthesized by dermal fibroblasts in malignant melanoma, and the decreased expression of lumican at the tumor margin may promote the proliferation of melanoma cells." (PMID 33493133, 2021). "Taking into consideration these data as well as the inhibitory effect of lumican in migration of Snail-transfected melanoma cells it is plausible to suggest that lumican prevents the remodeling of the distribution of major invadopodia markers in Snail-B16F1 melanoma cells." (PMID 33917849, 2021). "Furthermore, lumican attenuated the growth of melanoma cells and downregulated the response to the anticancer validated peptide TAX2." (PMID 34572532, 2021). "Our group has demonstrated the inhibitory effect of lumican on melanoma progression." (PMID 34638415, 2021). "Regarding melanoma, lumican also seems to be negatively correlated with its progression." (PMID 34572532, 2021). "Interestingly, lumican was previously shown to reduce melanoma tumor growth through the induction of apoptosis." (PMID 32548117, 2020). "In addition to its role as a regulator of extracellular matrix (ECM) integrity, lumican, a small leucine-rich proteoglycan, also exhibits anti-tumor properties in melanoma." (PMID 32548117, 2020). "Conversely, the overexpression of lumican in melanoma cells inhibited tumor formation in an animal model, whereas low expression levels of lumican and decorin are associated with a poorer patient survival in breast tumors and spindle cell carcinomas, respectively." (PMID 33202923, 2020). "Moreover, the effect of lumican-derived peptides on growth and migration of melanoma cells was previously demonstrated in vitro." (PMID 32548117, 2020). "The expression of lumican in melanomas inhibits cell invasion and tumor formation, whereas, in patients with lung adenocarcinoma, the level of lumican expression in the cancer cells is correlated with cell metastasis and tumor growth, but not with disease prognosis." (PMID 31963522, 2020). "In Snail-B16F1 cells, lumican inhibits migration, growth, and melanoma primary tumor development." (PMID 26930497, 2016). "A lumican-based strategy targeting Snail-induced MMP-14 activity might be useful for melanoma treatment." (PMID 26930497, 2016).
melanoma (continued). "Lumican was reported to inhibit melanoma and endothelial cell migration." (PMID 24098450, 2013). "The ECM component, lumican, may be considered as an anti-tumor molecule, since it was shown to decrease melanoma progression in vivo." (PMID 24098450, 2013). "Previous data from our laboratory demonstrated direct anti-tumor properties of lumican in melanoma." (PMID 23236386, 2012). "Similarly, lumican reduced invadopodia formation in melanoma cells." (PMID 39334952, 2024). "Moreover, LUM plays protection roles in cancer through inhibiting MT1-MMP in melanoma cells." (PMID 34310653, 2021). "Therefore, the decreased FAK phosphorylation and the inhibition of MMP-14 activity induced by lumican in melanoma cells might explain, at least in part, the anti-invasive effect of this SLRP." (PMID 33917849, 2021). "Altogether, these data demonstrated that lumican significantly inhibits lung metastasis in vivo, as well as cell invasion in vitro, suggesting that a lumican-based strategy targeting Snail-induced metastasis could be useful for melanoma treatment." (PMID 33917849, 2021). "Thus, a lumican-based strategy targeting the Snail-induced MMP-14 activity might be helpful for melanoma treatment." (PMID 34572532, 2021). "This may explain decreased melanoma cell growth and cell motility in the presence of lumican." (PMID 33917849, 2021). "Furthermore, the lumican protein core was shown to inhibit melanoma cells’ migration." (PMID 34572532, 2021). "Moreover, lumican was able to decrease melanoma cell lung metastasis." (PMID 24098450, 2013). "Lumican-derived peptides, such as lumcorin (17 amino acids) or L9M (10 amino acids), are able to inhibit the proteolytic activity of MMP-14 and melanoma progression." (PMID 34638415, 2021). "The potential anti-metastatic role of lumican in melanoma by inhibiting the membrane type matrix metalloproteinase MMP-14 activity and melanoma cell migration in vitro was also reported." (PMID 33917849, 2021). "Lumican, a small leucine-rich proteoglycan (SLRP), maintains ECM integrity and inhibits both melanoma primary tumor development, as well as metastatic spread." (PMID 34885059, 2021). "In contrast to the HT-144 melanoma cell line, L9Mc significantly inhibited the migration of B16F1 cells and the activity of MMP-14 but with less efficacy than lumican and lumcorin." (PMID 34638415, 2021). "Lumican, a small leucine-rich proteoglycan (SLRP), maintains extracellular matrix (ECM) integrity while inhibiting melanoma primary tumor development, as well as metastatic spread." (PMID 34885059, 2021). "It was reported that lumican inhibits the activity of metalloproteinase MMP-14 and melanoma cell migration in vitro and in vivo." (PMID 33917849, 2021). "It is worth noticing that lumican downregulates the MMP-14 gene expression in both Mock-B16F1 and Snail-B16F1 melanoma cells." (PMID 33917849, 2021). "We also showed previously that extracellularly added Lumican (LUM), that belongs to the family of PGs, inhibits MMP-14 activity induced by Snail in B16F1 melanoma cells." (PMID 32629890, 2020). "Overall, our study establishes for the first time a direct link between lumican expression and alterations in tumor ECM organization that support tumor growth in a melanoma preclinical model." (PMID 28794454, 2017). "In a mouse melanoma model of B16F1 injection, tumor formation was significantly inhibited when human lumican overexpressing cells were used." (PMID 26930497, 2016). "Since malignant melanoma represents one of the deadliest cancer types at the metastatic stage, the aim of the study was to investigate the effect of lumican on MMP-14 activity and migration capacities of Snail overexpressing melanoma cells." (PMID 26930497, 2016). "Lumican, a small leucine rich proteoglycan, inhibits MMP-14 activity and melanoma cell migration in vitro and in vivo." (PMID 26930497, 2016).
melanoma (continued). "The aim of this work was to investigate lumican effects on MMP-14 activity and migration of Snail overexpressing B16F1 (Snail-B16F1) melanoma cells and HT-29 colon adenocarcinoma cells." (PMID 26930497, 2016). "These preliminary data suggest that the L9M 10 aa peptide of lumican LRR9 can inhibit growth and migratory properties of melanoma cells." (PMID 24098450, 2013). "The genes detected as down-regulated in most metastatic melanomas, and that are therefore candidates for metastasis suppressors, are LUM (lumican), DCTN6 (dynactin 6) and DNCI2 (dynein intermediate chain 2)." (PMID 18211678, 2008). "The LUM protein has been shown to have both oncogenic (breast, pancreas, colorectal) and tumour suppressor (melanoma) activities, but to date there is no data for LUM from head and neck malignancies." (PMID 37760543, 2023). "In addition, we found that three cohorts of bladder cancer, glioblastoma, and melanoma with low LUM expressions had higher survival outcomes after ICB treatment, confirming the importance of low LUM levels in immunotherapy." (PMID 37692065, 2023). "Moreover, the stimulatory effect of SNAIL in the MMP-14 activity and the in vitro melanoma cell migration countered by lumican and its derived peptide in the MMP-14 activity led us to investigate the effect of lumican in vivo." (PMID 33917849, 2021). "Another study on melanoma showed that lumican was expressed in metastatic melanoma cells rather than normal melanocytes." (PMID 33493133, 2021). "Melanoma cells do not express lumican, but the increased expression of lumican to the peritumoral stroma is negatively correlated withthis tumor growth." (PMID 34572532, 2021). "The inhibition of melanoma cell migration by lumican was related to the inhibition of the phosphorylation of focal adhesion kinase (FAK), and as observed, a significant decrease of the ratio pFAK/FAK was also shown in presence of lumican." (PMID 33917849, 2021). "Thus, lumican can maintain skin ECM integrity by inhibiting MMPs activity, and consequently melanoma progression and epithelial-mesenchymal transition (EMT)." (PMID 34885059, 2021). "Thus, lumican is able to inhibit the remodeling of the skin ECM by inhibiting MMPs activity, and consequently melanoma progression." (PMID 32548117, 2020). "Moreover, previous studies showed the ability of lumican (and its derived peptides), in contrast to decorin, to inhibit MMP-14 activity in melanoma cells, where lumican directly interacts with MMP-14 and inhibits its activity." (PMID 32548117, 2020). "We observed that the genes DCN (decorin), LUM (lumican) and BGN (Bgn), which are members of the small leucine-rich proteoglycan (SLRP) family, were within the highest expressed ECM genes in both melanoma cells and fibroblasts." (PMID 28476030, 2017). "Collectively, it has been previously reported that lumican, among other functions, effectively regulates cell functional properties, expression of ECM effectors, EMT, invadopodia markers, morphology of invading breast cancer cells, as well as MMP-14 and cell migration in melanoma cells." (PMID 33917849, 2021). "Indeed, lumican inhibits the degradation of ECM by inhibiting MMP-14, then influencing integrin clustering, modulating focal adhesion site stability and FAK phosphorylation at Tyr-397, leading to the inhibition of melanoma cell migration." (PMID 34572532, 2021). "In addition, melanoma primary tumors treated with or without lumican-derived peptide were discriminated through infrared spectral imaging." (PMID 34885059, 2021). "In EPC, the β1 integrin expression was slightly increased in presence of lumican The distribution of actin cytoskeleton, which is altered in melanoma cells in presence of lumican, was not significantly remodelled in MSC and EPC in comparison to other ECM substrata." (PMID 23236386, 2012).
melanoma (continued). "L9Mc significantly inhibited the migration of murine B16F1 but not human HT-144 melanoma cells and the activity of MMP-14 but with less efficacy than lumican and lumcorin." (PMID 34638415, 2021).
breast carcinoma (33 papers, 2007 to 2025). "Its expression in breast cancer is controversial, but studies show that the downregulation of LUM in human breast cancers is associated with a worse prognosis." (PMID 36982287, 2023). "In this report, we evaluated the effects of lumican in respect to the ERs-associated breast cancer cell behaviour, before and after suppression of ERs, using scanning electron and confocal microscopies, qPCR and functional assays." (PMID 28332606, 2017). "Lumican and decorin appeared to be inversely regulated in association with breast cancer tumourigenesis." (PMID 28332606, 2017). "The overexpression of lumican in breast cancer tissues is associated with a high tumor grade, a low estrogen receptor (ER) expression level, and young age of patients." (PMID 25140302, 2014). "Using in situ hybridization and western blot techniques, LUM mRNA levels were significantly higher (P < 0.0001) in stroma associated with breast carcinoma compared with stroma associated with adjacent normal tissue in the same woman." (PMID 19036156, 2008). "Positive associations between decorin and lumican protein expression and mammographic density, a major risk factor for breast cancer, have also been observed." (PMID 19036156, 2008). "It is noteworthy that MG-stress-driven fine-tuning of the ECM consisted of the up-regulation of pro-metastatic genes but also the down-regulation of specific components such as lumican the reduced expression of which has been associated with poor prognosis in patients with breast cancer." (PMID 30674353, 2019). "It is worth noticing that lumican was found not only to significantly affect cell properties such as proliferation, migration and invasion, but also cell surface receptors, matrix macromolecules implicated in breast cancer progression and EMT markers." (PMID 28332606, 2017). "Notably, in breast cancer high stromal lumican expression is associated with high tumor grade and low estrogen receptor level." (PMID 25961303, 2015). "Although LUM rs2268578 was associated with breast cancer in the Mayo Clinic study, particularly ER-positive breast cancer, weaker and modest associations were observed in the SEARCH sample." (PMID 19036156, 2008). "Although LUM rs2268578 was associated with breast cancer in the Mayo Clinic study, particularly estrogen receptor-positive breast cancer, weaker and modest associations were observed in the SEARCH sample." (PMID 19036156, 2008). "The hypothesis that genetic variation in LUM is associated with breast cancer is based on a recent series of reports by Watson and colleagues of altered regulation of LUM in human breast tumors." (PMID 19036156, 2008). "The increased risk of breast cancer from LUM rs2268578 may be due to the positive association with ER-positive breast tumors in both the Mayo Clinic and SEARCH samples, although the analyses were underpowered and were not based on a priori hypotheses." (PMID 19036156, 2008). "We investigated associations of 14 common polymorphisms in the DCN and LUM genes with 798 breast cancer cases and 843 controls from Mayo Clinic, MN, USA." (PMID 19036156, 2008). "It is possible that the association between breast cancer risk and these inferred haplotypes may be attributable to LUM rs2268578 or a SNP in strong linkage disequilibrium with rs2268578 because this single SNP was also associated with risk in both the Mayo Clinic and SEARCH samples." (PMID 19036156, 2008). "Second, the TCGA BRCA dataset (n = 821) with PAM50 subtypes called by RNAseq was used to validate the differentially expression of COL2A1, COL11A1, COL6A1, COL6A2, THBS1 and LUM among four breast cancer molecular subytpes in an independent cohort." (PMID 40927672, 2025). "Functional proteomics suggested that collagen proteins, thrombospondin 1 and lumican are differentially expressed across breast cancer subtypes." (PMID 40927672, 2025).
breast carcinoma (continued). "We observed that colorectal, GBM, and breast cancer patients with high LUM expressions have good clinical responses to chemotherapy, while ovarian cancer patients with high LUM expressions are resistant to chemotherapies." (PMID 37692065, 2023). "Both breast cancer and pancreatic cancer cells have been documented to upregulate LUM, along with many other cancer types." (PMID 36873459, 2022). "It has been reported that LUM promoted epithelial-to-mesenchymal transition (EMT) in breast cancer and enhanced the migration and invasiveness of colon cancer cells through actin cytoskeletal organization remodeling." (PMID 34590603, 2021). "The proteoglycan lumican is known to play a role in estrogen-mediated functions of breast cancer cells, including EMT." (PMID 34282767, 2021). "A recent study in breast cancer in vitro showed that lumican treatment in combination with the knockdown of ERα and the suppression of ERβ can regulate these cells’ differentiation state, morphology, expression of matrix effectors, and cell behavior." (PMID 34572532, 2021). "Further studies investigated the role of LUM in promoting epithelial-to-mesenchymal transition (EMT) in breast cancer, and the depletion of LUM inhibited the proliferation and migration of bladder cancer cells by inactivating MAPK signaling." (PMID 33493133, 2021). "For example, several studies demonstrated that high LUM expression is related to the unfavorable prognosis of breast cancer and pancreatic carcinoma." (PMID 33493133, 2021). "In breast cancer, the expression of lumican in cancer cells is correlated with young age, high-grade tumor, and low expression of the estrogen receptor." (PMID 31963522, 2020). "For instance, a decrease of 2–3 times the normal expression has been reported for lumican in breast cancer tissue." (PMID 31437251, 2019). "Treatment of MCF7/SP10+ breast cancer cells with lumican induced a tendency to appear more globular and to form cell-cell junctions." (PMID 28332606, 2017). "On the other hand, lumican treatment of shERβΜDA-MB-231 breast cancer cells revealed a slight increase of the expression levels of the epithelial marker E-cadherin, whereas it decreased that of the mesenchymal marker vimentin." (PMID 28332606, 2017). "The effects of lumican were found to be related to the type of breast cancer cells and the ERα/β type." (PMID 28332606, 2017). "In this study, the obtained data concerning the mediation of breast cancer cell properties by lumican, clearly suggest significant alterations of the basal cell functional properties, such as proliferation, migration and aggressiveness." (PMID 28332606, 2017). "Specifically, we evaluated the effects of lumican on various types of breast cancer cells; one positive for ERα (MCF-7, low invasive) and another positive for the ERβ (MDA-MB-231, highly invasive) before and after knockdown of these ERs, respectively." (PMID 28332606, 2017). "In respect to breast cancer, low expression of lumican is correlated with the patients’ poor outcome." (PMID 28332606, 2017). "Treatment of MCF-7/SP10+ breast cancer cells with lumican affected the spindle-like morphology by reducing the characteristic mesenchymal morphology of these cells and increasing the number of cell-cell junctions." (PMID 28332606, 2017). "This potential effect of lumican on TGF-β signalling as a possible effector of EMT/MET would be of importance to be evaluated in breast cancer cells." (PMID 28332606, 2017). "Contrariwise, the 5 breast carcinoma and 5 ovarian carcinoma specimens were all strongly positive for lumican." (PMID 25961303, 2015). "Higher expression of LUM was found in breast cancer stroma as compared to the normal tissue and was found to be associated with low levels of estrogen receptor and higher tumor grade." (PMID 24086418, 2013).